DOK5 (docking protein 5)
Description:
DOK proteins are enzymatically inert adaptor or scaffolding proteins. They provide a docking platform for the assembly of multimolecular signaling complexes. DOK5 functions in RET-mediated neurite outgrowth and plays a positive role in activation of the MAP kinase pathway. Putative link with downstream effectors of RET in neuronal differentiation.
Synonyms: IRS-6; IRS6; C20orf180; dJ805C22.1
Tractability: No criterion of Open Targets' tractability assessment is met for any kind of drug.
Gene: Protein-coding gene on chromosome 20 (54,475,593 to 54,651,171, forward strand). Ensembl gene ENSG00000101134.
Subcellular location (Human Protein Atlas): Focal adhesion sites
Pathways (Reactome):
Developmental Biology: RET signaling
Gene Ontology:
Molecular function: signaling adaptor activity
Biological process: regulation of neurotrophin TRK receptor signaling pathway; cell surface receptor protein tyrosine kinase signaling pathway
Cellular component: cytosol
Genetic constraint (gnomAD): Loss-of-function variants: 23 observed, 34.96 expected, observed/expected ratio (o/e) 0.66, 90% interval 0.47 to 0.93. The upper end of that interval is the gene's LOEUF score, 0.93, which puts it in group 3 of 6, group 1 being the genes least tolerant of losing a copy. Missense variants: 337 observed, 356.24 expected, observed/expected ratio (o/e) 0.95, 90% interval 0.87 to 1.03. Synonymous variants: 136 observed, 129.73 expected, observed/expected ratio (o/e) 1.05, 90% interval 0.91 to 1.21.
Homologues: Orthologues: chimpanzee DOK5 (100% identical), macaque DOK5 (99% identical), guinea pig DOK5 (98% identical), mouse Dok5 (98% identical), dog DOK5 (98% identical), pig DOK5 (97% identical), rabbit DOK5 (96% identical), rat Dok5 (91% identical), tropical clawed frog dok5 (78% identical), Caenorhabditis elegans rog-1 (20% identical), Drosophila melanogaster Dok (18% identical), Drosophila melanogaster CG13398 (15% identical). Paralogues in human: DOK6 (70% identical), DOK4 (59% identical), DOK1 (25% identical), DOK2 (22% identical), DOK3 (21% identical), FRS2 (13% identical), FRS3 (13% identical).
Diseases named in the same sentence as DOK5 in open-access papers:
DOK5 is named in the same sentence as 38 diseases in open-access papers, as found by Europe PMC text mining. Sharing a sentence is not in itself a finding about the gene and the disease. The quoted sentences say what the papers report.
Obesity (4 papers, 2010 to 2025). Accumulation of substantial excess body fat. "From the 23 known genes and 13 Riken transcripts; Dok5, Mc3r, Bmp7, and Pck1 have been associated with obesity." (PMID 25613955, 2015). "In conclusion, we identified DOK5 as a novel gene modulating the susceptibility of obesity and diabetes in North Indian population of Indo-European ethnicity." (PMID 20187968, 2010). "We identified DOK5 as a novel susceptibility gene for obesity and type 2 diabetes in North Indian subjects." (PMID 20187968, 2010). "DOK5 has previously been associated with reduced BMI and protection against obesity in a North Indian population, where specific variants were linked to a lower risk of obesity." (PMID 40564227, 2025). "In the DOK5 gene, genetic variants were associated with obesity in North Indian patients." (PMID 30385857, 2018). "Association of DOK5 variants both with obesity and type 2 diabetes suggests that these variants might modulate type 2 diabetes susceptibility through obesity." (PMID 20187968, 2010). "Therefore, here for the first time, we explored DOK5 as a potential type 2 diabetes and obesity susceptibility gene in North Indian population which has a high risk of developing type 2 diabetes." (PMID 20187968, 2010). "Hence, for the first time, we explored DOK5 as a potential type 2 diabetes and obesity susceptibility gene." (PMID 20187968, 2010). "Association of DOK5 variants with obesity again suggests that these variants may modulate the susceptibility to type 2 diabetes through obesity." (PMID 20187968, 2010). "Therefore, here, we investigated a potential positional and functional candidate gene, DOK5 on chromosomal region 20q13, to identify novel susceptibility gene for type 2 diabetes and obesity." (PMID 20187968, 2010). "Because of its involvement in insulin signaling and immune responses which are the key modulating pathways in type 2 diabetes and obesity, DOK5 seems to be a convincing positional and functional candidate for type 2 diabetes and obesity." (PMID 20187968, 2010).
breast carcinoma (2 papers, 2022 to 2023). "It has also been studied in breast cancer, liver cancer, and colorectal cancer, and DOK5 gene expression in cancer tissues is higher than that in normal tissues." (PMID 35036444, 2022).
gastric cancer (2 papers, 2022 to 2023). A primary or metastatic malignant neoplasm involving the stomach. "Moreover, in patients with stomach cancer, the DOK5 expression level is also significantly different in different pathological stages, tumor differentiation, and T stages." (PMID 35036444, 2022). "Our research shows that DOK5 is related to the survival and prognosis of GC patients; therefore, this suggests that DOK5 may be a specific marker of gastric cancer." (PMID 35036444, 2022). "Hence, DOK5 might become a new gastric cancer biomarker and therapeutic target." (PMID 35036444, 2022). "DOK5 is shown to be involved in the invasion and metastasis of cancer specifically in gastric cancer, but it has not been well-studied in PCa." (PMID 37218885, 2023). "Nevertheless, the role of DOK5 expression in the prognosis of gastric cancer (GC) remains unclear." (PMID 35036444, 2022).
type 2 diabetes (2 papers, 2010 to 2015). "Association analysis of DOK5 SNPs revealed significant association of its variants with type 2 diabetes among normal-weight subjects." (PMID 20187968, 2010). "Therefore, future genetic and functional studies evaluating the association of genetic variants of DOK5 and deciphering their physiological effect and mechanisms are needed to further ascertain its role in the manifestation of type 2 diabetes." (PMID 20187968, 2010). "Hence, our data suggests that DOK5 might play a significant role in modulating the susceptibility of type 2 diabetes among normal-weight subjects in North Indian population." (PMID 20187968, 2010). "None of the DOK5 variants analyzed here showed association with type 2 diabetes." (PMID 20187968, 2010).
basal cell carcinoma (1 paper, 2022). A carcinoma involving the basal cells. "Melanoma, basal cell carcinoma, and hematopoietic cell lineage all proved that DOK5 influences the progression as well as the occurrence of tumors." (PMID 35036444, 2022).
cholangiocarcinoma (1 paper, 2022). A carcinoma that arises from the intrahepatic biliary tree (intrahepatic cholangiocarcinoma) or from the junction, or adjacent to the junction, of the right and left hepatic ducts (hilar cholangiocarcinoma). "However, DOK5 expression was significantly increased in cholangiocarcinoma (CHOL), liver hepatocellular carcinoma (LIHC), lung adenocarcinoma (LUAD), and stomach adenocarcinoma (STAD), compared to adjacent normal tissues." (PMID 35036444, 2022).
familial medullary thyroid carcinoma (1 paper, 2022). An instance of thyroid medullary carcinoma that is caused by an inherited modification of the individual's genome. "The receptor, tyrosine kinase c-Ret, has been found to be an oncogenic mutation in patients with multiple endocrine tumors and cancer syndromes with familial medullary thyroid carcinoma, and DOK5 can be directly associated with Y1062 of c-Ret, thereby enhancing the effect of c-Ret." (PMID 35036444, 2022).
leukemia (1 paper, 2022). A malignant (clonal) hematologic disorder, involving hematopoietic stem cells and characterized by the presence of primitive or atypical myeloid or lymphoid cells in the bone marrow and the blood. "Analysis shows that in contrast to the normal tissues, DOK5 was better expressed in GC, leukemia, lymphoma, and pancreatic cancer tissues." (PMID 35036444, 2022).
liver cancer (1 paper, 2022). An epithelial or non-epithelial malignant neoplasm that arises from the liver. "Based on results from 364 patients with liver cancer, poorer prognoses in terms of OS and DFS (P < 0.05) were associated with lower mRNA expression levels for DOK5." (PMID 35036444, 2022).
lung carcinoma (1 paper, 2022). "Conversely, DOK5 expression was not related with PFS and PPS in lung cancer." (PMID 35036444, 2022).
lymph node metastasis (1 paper, 2022). "Therefore, we further studied the link shared by the expression of DOK5 and clinicopathological boundaries and found that the DOK5 expression level had been associated with lymph node metastasis and T stage." (PMID 35036444, 2022). "It is worth noting that among patients with lymph node metastasis, patients with high DOK5 expression have a poorer prognosis (OS: stage N1, HR = 2.43, P < 0.001; stage N2, HR = 1.78, P < 0.05; stage N3, HR = 1.88, P < 0.05; stage N1+2+3, HR = 1.97, P < 0.001." (PMID 35036444, 2022). "Moreover, for patients with lymph node metastasis, patients with high DOK5 expression have a poor prognosis, while patients with low DOK5 expression have a better prognosis." (PMID 35036444, 2022). "In the end, in patients with lymph node metastasis, DOK5 expression level is also higher." (PMID 35036444, 2022).
oral squamous cell carcinoma (1 paper, 2022). "In the pathogenesis of oral squamous cell carcinoma, TNF-α can regulate EMT through the MAPK signaling pathway to promote cancer cell invasion and metastasis, and DOK5 also involved in MAPK (mitogen-activated protein kinase) signal pathway activation." (PMID 35036444, 2022).
cancer (3 papers, 2016 to 2023). A tumor composed of atypical neoplastic, often pleomorphic cells that invade other tissues. "In order to further study the prognostic potential of DOK5 in different cancers, the Kaplan-Meier plotter database was used to evaluate the prognostic value of DOK5 based on Affymetrix microarray." (PMID 35036444, 2022). "Our research shows that DOK5 is likely to be an oncogene that holds a crucial part in the development and occurrence of cancer." (PMID 35036444, 2022). "In order to determine the difference in the expression of DOK5 in tumors and normal tissues, we used the Oncomine database to analyze the DOK5 mRNA levels in normal tissues of different tumors and multiple cancer types." (PMID 35036444, 2022). "For more assessment of the DOK5 expression in human cancers, we made use of RNA-seq data using several malignant tumors found in TCGA for identifying the DOK5 expression." (PMID 35036444, 2022). "Therefore, we made use of the TIMER database for the identification of the relationship shared by the DOK5 expression and infiltrating immune cells in 32 cancers, including GC." (PMID 35036444, 2022). "Some of the prominent genes we identified through the networks are DOK5, APP, CTNND1, STX6, STX10, STX16, BACE1, and BACE2; which, agree with the regulation of various cancers based on their co-expression patterns in GeneMANIA." (PMID 37218885, 2023). "In order to study whether the expression of DOK5 is related to the prognosis of cancer patients, we used GEPIA and Kaplan-Meier plotter to evaluate the effect of DOK5 expression on survival." (PMID 35036444, 2022).
tumor (3 papers, 2012 to 2022). "In this study, we systematically assessed DOK5 expression in a variety of tumor forms involving GC, as well as its association with prognosis." (PMID 35036444, 2022). "Hence, the expression level of DOK5 is expected to be a potential diagnostic indicator for tumor staging in patients with GC." (PMID 35036444, 2022). "The results showed that in 32 tumor types, DOK5 expression was crucially related to CD4+ T cells, CD8+ T cells, neutrophils, macrophages, and dendritic cells." (PMID 35036444, 2022). "Our results clarified the significant role of DOK5 in the prognosis of GC and offer a potential mechanism by which DOK5 expression might monitor tumor immunity—regulation of the infiltration of immune cells in GC." (PMID 35036444, 2022). "Furthermore, we also explored the link shared by SCNA (somatic copy number alteration) of DOK5 gene and the level of GC tumor invasion." (PMID 35036444, 2022). "Therefore, we have reason to speculate that DOK5 may also participate in tumor progression through the MAPK pathway." (PMID 35036444, 2022).
DOK5 also shares sentences with these, for which no sentence is quoted: colorectal cancer (2 papers); glaucoma (2); American trypanosomiasis (1); bladder urothelial carcinoma (1); cardiovascular disease (1); Chagas disease (1); colorectal tumors (1); COVID-19 (1); diabetes (1); head and neck cancer (1); Huntington disease (1); infection (1); intracranial aneurysm (1); lung adenocarcinoma (1); lymphoma (1); malaria (1); melanoma (1); pancreatic cancer (1); prostate adenocarcinoma (1); prostate carcinoma (1); skin cutaneous melanoma (1); stomach cancer (1); thyroid carcinoma (1); uterine corpus endometrial carcinoma (1).